MTCH2 (mitochondrial carrier 2)
Diseases named in the same sentence as MTCH2 in open-access papers (continued):
Sharing a sentence is not in itself a finding about the gene and the disease.
prostate carcinoma (1 paper, 2025). A carcinoma that arises from epithelial cells of the prostate gland. "Bioinformatic analyses reveal that MTCH2 overexpression is associated with critical clinical parameters of prostate cancer." (PMID 39910035, 2025). "Single-cell sequencing further reveals elevated MTCH2 expression within prostate cancer epithelial cells." (PMID 39910035, 2025). "Our analysis demonstrated a higher number of MTCH2 mRNA transcripts in prostate cancer tissue (“Tumor”) compared to the normal prostate tissue (“Normal”)." (PMID 39910035, 2025). "The bioinformatic analyses demonstrated that MTCH2 is overexpressed in prostate cancer tissue and correlates with the key clinical parameters in patients." (PMID 39910035, 2025). "Single-cell sequencing data indicate elevated MTCH2 expression in the prostate cancer epithelium." (PMID 39910035, 2025). "Importantly, overexpression of MTCH2 in prostate cancer tissue was correlated with decreased disease-specific survival (DSS)." (PMID 39910035, 2025). "Additionally, MTCH2 expression was higher in prostate cancer tissue with prostate-specific antigen (PSA) levels ≥4 compared to those with PSA levels <4." (PMID 39910035, 2025). "Furthermore, we examined the expression levels of MTCH2 in primary prostate cancer cells derived from four CRPC patients, designated as “pPC-1”, “pPC-2”, “pPC-3”, and “pPC-4”." (PMID 39910035, 2025). "Moreover, MTCH2 expression was elevated in N1-stage prostate cancer tissue compared to N0-stage tissue." (PMID 39910035, 2025). "Subsequent WikPathway enrichment analysis of these common genes revealed significant associations of MTCH2 with metabolic reprogramming, tricarboxylic acid cycle (TCA) cycle, and sterol regulatory element binding protein (SREBP) signaling pathways in prostate cancer." (PMID 39910035, 2025). "Specifically, MTCH2 expression was significantly higher in the epithelial cells of the prostate cancer (“PRAD”) group compared to the normal prostate tissue (“NORM”) group." (PMID 39910035, 2025).
thymoma (1 paper, 2013). A neoplasm arising from the epithelial cells of the thymus. "In addition, other than the thymomas, the TSCCs showed lower mRNA expression of the MTCH2 gene that induces apoptosis by cooperation with tBID to facilitate BAX-mediated mitochondrial cytochrome c release." (PMID 24427739, 2013).
cancer (15 papers, 2008 to 2025). A tumor composed of atypical neoplastic, often pleomorphic cells that invade other tissues. "MTCH2 expression in epithelial cells progressively increases from normal tissues to early-stage cancer tissues, and further to advanced cancer tissues." (PMID 39948081, 2025). "The findings revealed a notable increase in MTCH2 expression within the cancer cell lines (PC9, A549, and H1299) in contrast to the normal cell line." (PMID 40510359, 2025). "In this study, we identified MTCH2 as a cancer‐promoting gene, with high MTCH2 levels predicting poor prognosis in patients with CRC." (PMID 40600459, 2025). "Recent studies have uncovered a critical role of MTCH2 in both physiological and pathological contexts, impacting metabolic diseases, neurodegenerative disorders, cancers, embryonic development, and reproduction." (PMID 39910035, 2025). "A dot plot and an expression density diagram both indicate that MTCH2 is highly expressed in cancer cell populations, with significantly higher levels in both LUAD and LUSC cells.The cancer cell population was further isolated and subsequently grouped." (PMID 39948081, 2025). "This analysis demonstrated that MTCH2 expression is particularly elevated in the proliferative cancer cell population." (PMID 39948081, 2025). "Recent studies have revealed the plethora of physiological and pathological functions of MTCH2 in metabolic diseases, neurodegenerative diseases, cancers, embryonic development, and reproduction." (PMID 41227324, 2025). "Analysis revealed that MTCH2 mRNA is highly expressed in epithelial cell populations of cancer tissues." (PMID 39948081, 2025). "These comprehensive findings consistently support the specific overexpression of MTCH2 in cancer cells within NSCLC mass, emphasizing its potential role as a critical marker and therapeutic target in the progression of NSCLC." (PMID 39948081, 2025). "Interrogation of TCGA Pan-Cancer dataset revealed that MTCH2 was highly expressed in several tumors despite different tissue origins, including cancers in the breast (BRCA), cervix (CESC), esophagus (ESCA), lung (LUSC) and brain (GBM)." (PMID 33509092, 2021). "The mitochondrial carrier homolog-2 (Mtch2) protein regulates membrane permeability and apoptosis and its suppression by miR-135b promotes certain carcinomas." (PMID 26681200, 2015). "This indicates a cancer cell-type-specific response to MTCH2 silencing in apoptosis induction." (PMID 39948081, 2025). "In addition, single-cell sequencing data revealed higher MTCH2 expression levels in cancer cells of NSCLC tumor mass." (PMID 39948081, 2025). "Studies have suggested that MTCH2 plays an oncogenic role in several cancers." (PMID 39910035, 2025). "Single-cell sequencing data also showed elevated MTCH2 levels in NSCLC cancer cells within tumors." (PMID 39948081, 2025). "Additionally, the correlation between MTCH2 expression levels and clinical staging parameters (N stage, T stage, and overall clinical stage) reinforces its role in cancer progression." (PMID 40510359, 2025). "The expression level of MTCH2 in various types of cancer tissues increased." (PMID 33299884, 2020). "Recent research suggests that MTCH2 may play an oncogenic role in human cancers." (PMID 39948081, 2025). "Research has indicated that MTCH2 could act as a pro-cancerous gene in various cancers." (PMID 39948081, 2025). "To validate our findings, we evaluated MTCH2 expression levels in CRC and normal tissue samples from two databases: The cancer genome Atlas (TCGA) and gene expression omnibus (GEO) (GSE20842 and GSE103512)." (PMID 40600459, 2025). "The PT complex downregulated the gene expression of kinesin-1 light chain 2 (KLC2), mechanosensing PIEZO2, mitochondrial carrier homolog 2 (MTCH2), and ZDHHC14, which are known to enhance the invasion and migration of cancer cells." (PMID 38027033, 2023).
cancer (continued). "Conversely, expression level of MTCH2 in seven (CHOL, COAD, KICH, KIRC, KIRP, PAAD, and THCA) types of cancer was lower than that in the corresponding normal tissues." (PMID 33299884, 2020). "We functionally confirmed this association in siRNA knockdown experiments of five PGC genes (p53CSV, MAP3K11, MTCH2, CPSF6, and SKIP), which either directly enhanced the invasive capacities or inhibited the proliferation of AGS cancer cells." (PMID 18636107, 2008). "MTCH2 and HSPA6 play various roles in different cancers but have not been associated with CRC." (PMID 35459861, 2022). "Furthermore, associations between MAP3K11, MTCH2 and CPSF6 to cancer have also not been previously reported." (PMID 18636107, 2008). "In epithelial cells, pEpi1 and pEpi2, MTCH2 knockdown using shMTCH2-S1 did not significantly increase Caspase-3 activity or nuclear TUNEL staining, again supporting a cancer cell-specific effect by MTCH2 knockdown." (PMID 39910035, 2025).
tumor (14 papers, 2016 to 2025). "The pathway enrichment analysis of DEGs in tumor cells suggested a relationship between MTCH2 and the ferroptosis‐associated biological pathway, further supporting our in vitro results." (PMID 40600459, 2025). "We found that MTCH2 expression was significantly associated with depth of invasion (P = 0.022), lymph node metastasis (P = 0.019), and tumor‐node‐metastasis (TNM) stage (P = 0.029)." (PMID 40600459, 2025). "Subgroup analyses revealed that MTCH2 overexpression was associated with advanced clinical T-stage and a higher tumor grade." (PMID 39910035, 2025). "Our results revealed that the proportions of various cell types were significantly altered in MTCH2cKO mice, providing a novel insight into the mechanisms underlying MTCH2‐regulated tumor progression." (PMID 40600459, 2025). "We identified MTCH2 (Chr11: 47647265 A>G) gene mutation as putative deleterious in the aggressive tumor studied." (PMID 36980325, 2023). "Furthermore, Fer‐1 rescued the inhibition of mouse tumor organoid growth that had been induced by MTCH2 deficiency, and erastin markedly enhanced the MTCH2 depletion‐induced inhibition of proliferation." (PMID 40600459, 2025). "Notably, variant prioritization after annotation indicated that the MTCH2 (Chr11: 47647265 A>G) gene sequence change was putative deleterious in all of the aggressive tumor samples." (PMID 36980325, 2023). "Notably, among the 81 alterations, only the mitochondrial carrier homolog 2 (MTCH2) gene mutation (Chr11: 47647265 A>G) was observed to be common (overlapped) across all the five tumor samples studied." (PMID 36980325, 2023). "Hence, decreased expression of the mitochondrial transporter MTCH2, a pro-apoptotic gene, was associated with enhanced invasiveness and tumor progression in various tumor types." (PMID 30618566, 2018). "The sgMTCH2‐mediated inhibition of cell proliferation was affirmed by EdU (5‐ethynyl‐2′‐deoxyuridine) staining of tumor cells, which was significantly decreased in MTCH2 knockout cells." (PMID 40600459, 2025). "The findings corroborated that the expression levels of the MTCH2 protein were markedly increased in the tumor tissues." (PMID 40510359, 2025). "The results of pairwise analysis also confirmed this finding, indicating a significant disparity in MTCH2 expression between tumor and normal tissues from the same patient." (PMID 40510359, 2025). "Recent studies highlight MTCH2 as a critical regulator of mitochondrial metabolism and energy homeostasis in tumor progression." (PMID 40600459, 2025). "Our analysis revealed an increased presence of MTCH2 mRNA transcripts in LUAD tissues (“Tumor”) compared to normal lung tissues (“Normal”)." (PMID 39948081, 2025). "Of these, 413 genes were upregulated in the high-expression cohort, while 505 genes were upregulated in the low-expression cohort, indicating the significant impact of MTCH2 expression on tumor gene expression profiles." (PMID 40510359, 2025). "The function of MTCH2 was further evaluated in CRC xenografts with MTCH2 knockout, which indicated that suppression of MTCH2 inhibited tumor growth, as reflected by reductions in tumor size, weight, and volume." (PMID 40600459, 2025). "EdU and Transwell assays proved that MTCH2 depletion combined with sorafenib remarkably suppressed tumor growth and migration." (PMID 40600459, 2025). "As expected, the violin plot showed that MTCH2 expression was significantly downregulated in tumor cells of MTCH2cKO mice, validating the knockout efficiency." (PMID 40600459, 2025). "Subsequently, the results of cytological experiments showed that knockout of MTCH2 inhibited tumor progression and metastasis by inducing ferroptosis." (PMID 40600459, 2025). "Subsequent extraction and sub-clustering of epithelial cells demonstrated that MTCH2 was predominantly distributed in tumor epithelium." (PMID 39910035, 2025).
tumor (continued). "Additionally, compared with the control tumor group, decreased numbers of liver metastatic nodules and lower liver weights were observed in the MTCH2 knockout tumor group." (PMID 40600459, 2025). "A subsequent Transwell assay confirmed that both migration and invasion capabilities of these cell lines were markedly suppressed after MTCH2 knockdown, indicating that MTCH2 might be essential in the processes of tumor cell invasion and metastasis." (PMID 40510359, 2025). "Moreover, the analysis of MTCH2 protein expression revealed an upregulation in tumor tissues from six representative patients (labeled as “T1” to “T6”)." (PMID 39948081, 2025). "Furthermore, MTCH2 knockout decreased the expression of Ki67, a biomarker of tumor proliferation in vivo." (PMID 40600459, 2025). "Considering the synergistic anti‐tumor effects of MTCH2 silencing and ferroptosis‐inducing agents in CRC cells, we next sought to investigate whether MTCH2 could affect sorafenib treatment of CRC liver metastasis." (PMID 40600459, 2025). "Inhibiting MTCH2 decreased tumor growth and induced differentiation of AML cells." (PMID 33509092, 2021). "Higher MTCH2 expression was observed in patients with advanced stages (T4, N2, stage III), suggesting its possible contribution to tumor aggressiveness and metastatic potential." (PMID 40510359, 2025). "Considering that the conditional knockout of MTCH2 applied to intestinal tissues, we focused on CRC tumor epithelial cells to describe the transcriptome landscape." (PMID 40600459, 2025). "Other noteworthy genes included DSPP, PER3, MTCH2, and KRT18, all have been reported with important roles in tumor formation and development." (PMID 32231683, 2020). "Induction of Mimp/Mtch2 in DA3 mouse mammary carcinoma cells alters Met signaling cascade, its induced motility, invasion in vitro and tumor growth in vivo." (PMID 27359329, 2016). "MTCH2 knockdown markedly suppressed LUAD cell proliferation, migration, and invasion, and induced G0/G1 phase cell cycle arrest, indicating its potential role as a tumor-promoting gene and unfavorable prognostic factor." (PMID 40510359, 2025). "Collectively, these results provided further evidence that MTCH2 depletion in tumor cells might enhance ferroptosis in CRC, leading to tumor suppression." (PMID 40600459, 2025). "Additionally, MTCH2 mRNA expression was compared between normal and tumor tissue samples from 30 pairs of LUAD patients, revealing a significant upregulation of MTCH2 expression in the tumor tissues." (PMID 40510359, 2025). "The heatmap showed that 12 tumor suppressors formed into two clusters: cluster 1 contains seven downregulated tumor suppressors including PTEN, PSME1, DNAJB1, HSPH1, DEDD2, PAK1IP1, and MIR1244-3; and cluster 2 contains five upregulated tumor suppressors (OSGIN1, IFI27L1, MTCH2, NKD2, and IBTK)." (PMID 34571936, 2021). "Several outlier genes whose knockdown confers striking vulnerability are tumor suppressors including APC, PHLPP1 and SPEN, while a number of other candidates have been reported to harbor anti-oncogenic activities such as the pro-apoptotic gene MTCH2 and the anti-metastatic RNA chaperone RBM47." (PMID 27296290, 2016).
metabolic disorders (3 papers, 2017 to 2025). "Thus, targeting MTCH2 could provide a new therapeutic avenue for metabolic disorders." (PMID 28276496, 2017).
neurodegenerative disease (2 papers, 2024 to 2025). A disorder of the central nervous system characterized by gradual and progressive loss of neural tissue and neurologic function. "This included two known proteins associated with MERCS, MFN2 and TOMM40, as well as neurodegenerative disease-associated genes such as WIPI2, CLASRP, BAG6, SOD1 and FUS which increase MERCS and MTCH2 and PARL which decrease MERCS." (PMID 38467609, 2024).
bacterial infection (1 paper, 2026). "Accordingly, MTCH2 depletion decreases not only apoptosis sensitivity but also sublethal mitochondrial permeabilization during bacterial infection, mitochondrial DNA release into the cytosol and cGAS-STING activation under impaired caspases." (PMID 42056306, 2026).
colorectal (1 paper, 2025). "Functionally, loss of MTCH2 inhibits azoxymethane (AOM)/dextran sodium sulfate (DSS)‐induced colorectal tumorigenesis in MTCH2cKO mice and leads to accumulation of ferrous ion and enhances ferroptosis of CRC in vitro and in vivo." (PMID 40600459, 2025).
neurological diseases (1 paper, 2024). "Additionally, the effects of MTCH2 on neurological diseases and adipocyte differentiation have been increasingly recognized in recent years." (PMID 39588545, 2024).
psychiatric disorder (1 paper, 2024). A disorder characterized by behavioral and/or psychological abnormalities, often accompanied by physical symptoms. "In summary, MTCH2 may be a common risk gene for psychiatric disorders and HEM, highlighting the role of mitochondrial dysfunction in the nervous system." (PMID 39588545, 2024).
MTCH2 also shares sentences with these, for which no sentence is quoted: glaucoma (3 papers); diabetes (2); Hyperinsulinemia (2); adenocarcinoma of the breast (1); astrocytoma of the brain (1); cardiovascular disease (1); cervical cancer (1); cognitive decline (1); Hepatic steatosis (1); lymphoma (1); non-small cell lung carcinoma (1); ovarian carcinoma (1); Parkinson disease (1); rectum adenocarcinoma (1); small cell lung carcinoma (1).